CAV1 (caveolin 1)
Diseases named in the same sentence as CAV1 in open-access papers (continued):
Sharing a sentence is not in itself a finding about the gene and the disease.
cancer (continued). "The reduction or dephosphorylation of Cav-1 can release Mfn2 and Drp1, promote mitochondrial dynamics and mitophagy, and reduce the accumulation of damaged mitochondria, thereby enabling cancer cell survival and affecting cancer treatment." (PMID 41030451, 2025). "Given the ability of EVs to travel long distances, Cav1-positive EVs may also play a role in pre-metastatic niche formation, priming distant tissues for colonization by cancer cells." (PMID 40963741, 2025). "Cav1 supports cancer cell survival under metabolic stress, hypoxia, and oxidative stress." (PMID 40963741, 2025). "The major constituent proteins of caveolae are dynamin‐2 (DNM2) and caveolin‐1 (CAV1), which are involved in endosome formation and the regulation of several parameters related to cancer progression, including cancer cell migration, metastasis, angiogenesis, and proliferation." (PMID 40419438, 2025). "However, the precise mechanisms by which Cav1 contributes to cancer progression through TEVs remain to be fully elucidated." (PMID 40963741, 2025). "In cancers where Cav1 is downregulated, restoring its expression could increase sensitivity to chemotherapy and radiation therapy, inhibit pro-survival pathways (e.g., PI3K/AKT), and improve the efficacy of targeted therapies like EGFR inhibitors." (PMID 40963741, 2025). "CAFs expressing Cav‐1 generate matrix stiffening and alignment, thereby promoting cancer invasion." (PMID 41377763, 2025). "Integrating Cav1-based strategies into clinical practice could be a game changer in cancer diagnosis, prognosis, and treatment, ultimately improving patient outcomes and advancing the field of precision oncology." (PMID 40963741, 2025). "Cav-1 exhibits anti-cancer as well as cancer-promoting properties." (PMID 40579643, 2025). "So, the Cacna1d, Kcnj12 Tgfb2, Cav1, Mecom, Kitlg, and Bmp2 genes had associations with any of the five pathways of PC1 (glutamatergic synapse, cholinergic synapse, proteoglycans in cancer, pathways in cancer, and MAPK signaling pathway)." (PMID 40076966, 2025). "However, studies have revealed that Cav1 can also be found as a secreted protein, functioning outside the cell to influence intercellular communication, inflammation, cancer progression, and tissue repair." (PMID 40963741, 2025). "Therefore, intervening in the Cav-1/ROCK1/Parkin axis can improve resistance to cisplatin in cancer treatment by inhibiting mitophagy." (PMID 41030451, 2025). "Furthermore, we shed light on the involvement of the caveolar protein caveolin-1 in EV biology, including its role in EV biogenesis, uptake, and impact on recipient cells from a cancer-specific perspective." (PMID 40963741, 2025). "Considering that the arrangement of substrate fiber directly affects the morphological features of cancer cells, we wondered whether Cav-1 could respond to the changes of ECM topological cues." (PMID 39318372, 2024). "Because Ago2/CAV1 interaction is present in cancer cells but not in normal cells, we assume that this interaction is associated with certain cancer cell-specific behaviors." (PMID 38649663, 2024). "We observed that S387 phosphorylation of Ago2, the determinant of Ago2 association with endosomes in cancer cells, did not affect Ago2/CAV1 interaction (Fig. EV1H)." (PMID 38649663, 2024). "We further evaluated whether the elevated miRNAs in cancer cells in which Ago2/CAV1 interaction is maintained could be released via EVs into the circulatory system and be detected in plasma as biomarkers." (PMID 38649663, 2024). "In addition, blockage of Ago2/CAV1 interaction in A549 cancer cells with P2 peptides increased the cells’ resistance to disassociation through 0.05% trypsin treatment, which is an epithelial phenotype." (PMID 38649663, 2024). "Since shCav-1 cells grown on aligned fibers showed an abnormal actin stress fiber network, we wondered whether this cytoskeleton defect induced by Cav-1 silence was involved in cancer cell migration and motility." (PMID 39318372, 2024).
cancer (continued). "Taken together, our findings revealed the Cav-1 is indispensable for the cellular response to topological change of ECM, and that the Cav-1/YAP axis is an attractive target for inhibiting cancer cell directional migration which induced by linearization of ECM fibers." (PMID 39318372, 2024). "To understand the underlying mechanism of Ago2/CAV1 interaction differently mediated by Ago2 lysine 212 in cancer cells and normal epithelial cells, we investigated the regulation of Ago2/CAV1 interaction through modification on Ago2 lysine 212, which interferes with the positive charge of lysine." (PMID 38649663, 2024). "The elevated miRNA-3613-3p in cancer cells with Ago2/CAV1 interaction can be released via EVs." (PMID 38649663, 2024). "CAV1 promotes metastasis and multi-drug resistance in late-stage cancer." (PMID 39494337, 2024). "In A549Ago2-KO/HA-AID-Ago2Wt/HA-Ago2∆ cells treated with IAA, which only expressed HA-Ago2∆, CAV1 was not precipitated with HA-Ago2∆ by anti-HA antibodies, indicating that Ago2/CAV1 interaction was blocked in IAA-treated cancer cells with an auxin-inducible degron system (Fig. EV3Ci,Cii)." (PMID 38649663, 2024). "We therefore set out to investigate whether Ago2/CAV1 interaction, as a secondary event, regulates miRNA-mediated mRNA suppression in cancer cells, using miRNA-3613-3p as an example." (PMID 38649663, 2024). "In another study, Caveolin-1 was shown to inhibit ferroptosis and promote cancer progression." (PMID 38791000, 2024). "Moreover, we also observed a selectivity of Fmoc-FF NGs towards cancer cell lines overexpressing the protein caveolin-1, such as MDA-MB-231 cells." (PMID 38688930, 2024). "Mechanistically, caveolin-1(Cav-1)-expressing cancer cells grown on aligned fibers exhibit increased integrin β1 internalization and actin polymerization, which promoted stress fiber formation, focal adhesion dynamics and YAP activity, thereby accelerating the directional cell migration." (PMID 39318372, 2024). "For instance, the down-regulation of CAV1 subsequently enhanced the invasion of cancer cells." (PMID 38254351, 2024). "We examined whether Ago2/CAV1 interaction is required for cancer cell dissemination from primary tumors." (PMID 38649663, 2024). "Nevertheless, the evidence from other available studies would suggest that CAV1 could act as a suppressor in early stages of cancer but become a promoter during metastasis." (PMID 39596307, 2024). "Therefore, further research is required on the effects of Ago2/CAV1 interaction on cancer therapy and the methods of selectively targeting Ago2/CAV1 interaction in clinical cancer therapy." (PMID 38649663, 2024). "The hallmarks of cancer-fibroblast interactions, consisting of caveolin 1 (Cav1) and mono-carboxylate transporter 4 (MCT4) (metabolic coupling markers), along with IL-6, TGFβ, and lactate secretion, are considered robust biomarkers predicting recurrence and metastasis." (PMID 38361760, 2024). "It supports that Ago2/CAV1 interaction is not predominantly responsible for Ago2 association with endosomes in cancer cells." (PMID 38649663, 2024). "Cav1-driven regulation of the signaling cues is critical in cancer." (PMID 38397421, 2024). "A majority of CEACAM6 on the surfaces of cancer cells can interact with other members of the CEA family on the surface of cancer cells in an interaction called cross-linking, which results in a significant increase in c-Src kinase activity and caveolin-1 phosphorylation." (PMID 38796667, 2024). "Moreover, different types of leukemic cell types overexpress caveolin-1, previously identified as the main entrance gate for Fmoc-FF nanoparticles in cancer cells making them sensibly more prone to endocite NPs." (PMID 38688930, 2024). "Furthermore, disrupting Ago2/CAV1 interaction also decreased the level of miRNA-3613-3p in the cancer cell-derived EVs." (PMID 38649663, 2024).
cancer (continued). "Furthermore, the levels of HA-Ago2Wt overlapping with CAV1 in A549Ago2-KO/HA-Ago2Wt cancer cells (arrowheads) were higher than that of CBM-deleted HA-Ago2∆ in A549Ago2-KO/HA-Ago2∆ cells (Dii)." (PMID 38649663, 2024). "To examine whether blockage of Ago2/CAV1 interaction directly affects miRNA-mediated mRNA repression, we overexpressed miR-3613-3p mimics in A549 cancer cells." (PMID 38649663, 2024). "It has been proven that the main metabolic coupling phenotype of cancer-associated fibroblasts (CAF) is a lack of Cav1 and a gain of MCT4." (PMID 38361760, 2024). "The CAV1-associated inhibition of PP1 increases the phosphorylation of various substrates, including ERK1/2, PDK1 and protein kinase B (AKT), which contributes to the survival, proliferation and invasive ability of cancer cells." (PMID 39339236, 2024). "Hence, Ago2/CAV1 interaction regulates the expression of certain miRNAs and is required for the miRNA-mediated mRNA repression in cancer cells (e.g., miR-3613-3p)." (PMID 38649663, 2024). "Caveolin-1 (CAV-1) is an important constituent protein of special membrane depression called fossa and a potential target for the prevention of cancer drug resistance and improvement of the clinical prognosis of various kinds of malignant tumors." (PMID 36874003, 2023). "Cav1 may be closely related to the progression of some malignant tumors, such as bladder cancer, ovarian cancer, lung cancer, among which its role in PCa being the most extensively explored." (PMID 37910338, 2023). "Therefore, we surmise that CAV1-mediated endocytosis increases the chance of survival during the colonization process at the metastatic site, which is a harsh process for cancer cells." (PMID 37919422, 2023). "In addition, caveolae and Cav1 can be potentially targeted in a translational context based on their relevance in certain pathological conditions, such as cancer or fibrotic diseases." (PMID 36980283, 2023). "Although studies have revealed that Cav-1 levels were elevated in patients with advanced cancer, whether Cav-1 affects BC lung metastasis by influencing the formation of pre-metastatic niche (PMN) through exosomes has not been explored." (PMID 37056561, 2023). "Furthermore, many studies demonstrated that caveolin-1 contributes significantly in the modulation of multiple cellular processes of cancer, including migration, metastasis, survival, and angiogenesis." (PMID 37576808, 2023). "However, some studies have come to the opposite conclusion, suggesting that Cav-1 expression in CAFs is a potential indicator of cancer progression." (PMID 37143134, 2023). "Caveolin-1 (CAV1), an oncogenic membrane protein related to endocytosis, extracellular matrix organization, cholesterol distribution, cell migration, and signaling has been linked to several cancers." (PMID 37122535, 2023). "In addition, Perex showed anti-cancer properties and inhibited the proliferation, migration, and invasion of MDA-MB-231 cancer cells that have high levels of caveolin-1 compared with other cancer and normal cells." (PMID 37958616, 2023). "The role of cav1 in cancer depends on the cell type and cancer stage 42-44." (PMID 37928877, 2023). "CAV1 expression differs among various cancer types and exhibits the dual role of this protein." (PMID 36036057, 2023). "In addition, CAV1 was highly expressed in cancer stem cells (CSCs) and modulated CSCs’ chemosensitivity." (PMID 37642765, 2023). "In the in vivo studies, combination therapy using an inhibitor of miRNA-1246 and paclitaxel led to the significant inhibition of tumor growth, which was associated with reduced proliferation of cancer cells, downregulation of PDGFRβ, and upregulation of Cav1 in cancer tissue." (PMID 37736898, 2023). "Moreover, sublethal doses of hydrogen peroxide induce caveolin-1 (Cav-1), which potentiate cancer cells to resist anoikis and allows anchorage-independent growth through Akt signaling." (PMID 37568652, 2023).
cancer (continued). "Again, these data suggest that cav1-pY14 promotes cancer cell migration, invasion, and metastasis." (PMID 37928877, 2023). "Of interest is the observed downregulation of CAV1 and CD36, both of which are involved in lipid metabolism and metabolic reprogramming of MDSC, and mycobacterial infections, and are associated with poor clinical outcomes in malignant tumors." (PMID 35356003, 2022). "Furthermore, Cav1 increased glucose uptake and stimulated the transcription of glucose transporters to produce ATP through the glycolytic pathway in cancer and normal cells." (PMID 36266374, 2022). "Thus, the increase in CAV1 expression in SH-SY5Y after CDDP treatment in the co-culture and monoculture confirmed the magnification of the CAV1-dependent invasive, migratory, and metastatic properties of the cancer cells." (PMID 36354566, 2022). "In the future, targeting caveolae-associated proteins, especially CAV1 and CAVIN1, may unravel a new paradigm in the treatment of drug resistance in cancer." (PMID 35158857, 2022). "In addition, we observed that CAV1 blocks the mitochondrial complex IV, thereby promoting the Warburg effect and the acquisition of more aggressive cancer cell traits." (PMID 35740528, 2022). "This evidence suggests that CAV1 expression in these cancer cells favors aerobic glycolysis." (PMID 35740528, 2022). "Caveolin-1 expression has also been investigated for human UC, both in the bladder and the upper urinary tract, and correlated with clinicopathological factors and cancer progression." (PMID 36299636, 2022). "Thus, activated fibroblasts/CAFs with low CAV1 levels are predestinated to fuel adjacent cancer cells." (PMID 35155239, 2022). "Also, transfecting radiosensitive A549 cells with Cav1 expressing lentivirus conferred dose-dependent radio-resistance to these cancer cells." (PMID 35620343, 2022). "As expected, silencing CAV1 in CAFs attenuated their ability to promote pancreatic cell proliferation, colony formation, sphere formation, and apoptosis resistance, similar to the cancer phenotypes induced by circFARP1 or LIF depletion." (PMID 35045883, 2022). "Caveolin-1 (Cav1) can stimulate Akt signaling and increase glycolysis in cancer cells." (PMID 36406265, 2022). "To assess which molecules could be involved in the HMPSNE- or AOAA-induced inhibition of Cyr61 release, we have measured Snail and Caveolin-1 expression, two molecules that are known to be involved in the promotion of CyR61 secretion from various cancer cells." (PMID 36113340, 2022). "Here the authors show that survival benefit to anti-HER2 antibody Trastuzumab is reduced in GC patients with high levels of the caveolin-1 and that, in preclinical cancer models, antibody drug efficacy can be improved by modulating caveolin-1 levels with cholesterol-depleting drugs, statins." (PMID 35534471, 2022). "Caveolin-1 (CAV-1) expression was inversely associated with NRF2 or SOD-2, which could predict the progress of more aggressive forms of cancer." (PMID 36289931, 2022). "We first investigated whether Cav1 expression contributes to the inhibitory effects of Kv11.1 activation on cancer cell migration." (PMID 35954304, 2022). "We therefore hypothesized that the dephosphorylation of Cav-1 induced by the pharmacologic Kv11.1 activator NS1643 may be a novel mechanism for regulating cancer cell migration and metastasis." (PMID 35954304, 2022). "This suggests that CAV1 expression may affect the sensitivity of cancer cells also towards radiation therapy." (PMID 35158857, 2022). "Meanwhile, CAV-1 affects cell metabolism by regulating glycolysis, mitochondrial bioenergetics, glutaminolysis, fatty acid metabolism, and autophagy, all of which are related to cancer growth and carcinogenesis." (PMID 35682652, 2022).
cancer (continued). "As CAV1 is an important regulator of cholesterol homeostasis, and cancer cells—besides its decisive impact on membrane physical properties—utilize cholesterol to satisfy their increased nutrient demands, the cholesterol contents of the different CAV1 variants were determined." (PMID 35155239, 2022). "In this study, we evaluated the effect of CAV1 on the metabolic phenotype of cancer cells and observed that expression of CAV1 decreases oxygen consumption in metastatic cells, by blocking mitochondrial complex IV, and induces an increase in ROS at the mitochondrial and cytoplasmic levels." (PMID 35740528, 2022). "The relationship of CAV1 expression in CAFs and clinical prognosis and biological significance may vary according to the kind of cancer." (PMID 35045883, 2022). "However, the down-regulation of Cav1 has been reported in the development and progression of different cancer types cutaneous including lung, colon, and breast cancer." (PMID 35897965, 2022). "On the contrary, targeting fibroblastic CAV1 or more precisely stabilizing CAV1 levels in stromal fibroblasts could be a promising additional anti-cancer strategy, presumably concerning radiosensitization." (PMID 35155239, 2022). "Finally, caveolin-1 is also an inhibitor of the TGF-β signaling pathway, with an impact on the crosstalk between epithelial cancer cells and cancer-associated fibroblasts." (PMID 36430209, 2022). "Finally, we corroborated the relevance of the CAV1-induced metabolic switch on cancer cell aggressiveness." (PMID 35740528, 2022). "Caveolin-1 (Cav-1, a membrane-bound scaffolding protein involved in endocytosis, signaling, cell motility, and cholesterol distribution) may also contribute to cancer progression by controlling the metabolism of CAFs, according to more recent research." (PMID 35813829, 2022). "In fact, Cav1 inhibits Bax-dependent cell death, helping cancer cells to escape chemotherapy." (PMID 34196606, 2021). "However, recent evidence shows that Cav-1 is also involved in metabolic alterations in several different cell types, such as hepatocytes and cancer cells." (PMID 34572135, 2021). "And GSEA revealed AREG, CAV1 and STAG3 were associated with dysregulated pathways in cancer." (PMID 33712015, 2021). "Several studies have observed loss of Cav-1 staining specifically in OvCa stromal cells, suggesting Cav-1 may be a marker of CAFs and poor survival in OvCa, as in other cancers." (PMID 34813586, 2021). "Expression of CAV1 protein in cancer cells is significantly associated with histological subtype of EOC, suggesting that CAV1 could serve as a useful prognostic biomarker and candidate therapeutic target in EOC." (PMID 34234869, 2021). "The protein Cav-1 responsible for the formation of caveolae is upregulated in cancer cells, and since endocytosis of albumin is mainly mediated through caveolae, the accumulation of albumin in cancer sites is further enhanced." (PMID 34298666, 2021). "Breast invasive carcinomas (BRCA) have the most dramatic decrease of CAV1 in cancer tissues." (PMID 34786475, 2021). "Importantly, this group of fibroblast cells expressed the markers for cancer‐associated fibroblasts (CAFs) including ACTA2 (encoding α‐SMA), PDGFRA, PDGFRB, DDR2, FAP, and CAV1." (PMID 34459128, 2021). "Cav1 localizes not only to the plasma membrane, but also to mitochondria, where it participates in the regulation of cell bioenergetics and apoptosis and, consequently, in cancer progression." (PMID 34196606, 2021). "Furthermore, chrysotobibenzyl was shown to suppress cancer cell migration via a Cav-1-dependent integrin switch." (PMID 33920031, 2021). "Furthermore, the reduced expression of Cav-1 in the ‘reactive’ or desmoplastic stroma of malignant tumors correlates with more aggressive disease and advanced stage." (PMID 34813586, 2021). "Various pieces of evidence have revealed the role of Cav-1 in the regulation of cancer metastasis." (PMID 33920031, 2021).